ARG1 (arginase 1)
Diseases named in the same sentence as ARG1 in open-access papers (continued):
Sharing a sentence is not in itself a finding about the gene and the disease.
tumor (continued). "In RCC, total MDSCs, G-MDSCs, and immature-MDSCs have been correlated with increasing tumor grade and stage, and are functionally immunosuppressive through arginase-1 production." (PMID 34831452, 2021). "Some approaches have been made in the use of PDE5 inhibitors that can block the production of nitric oxide and arginase 1 and restore the function of tumor-specific T cells." (PMID 33718200, 2021). "Most investigations on the influence of arginine metabolism on T cells have focused on mechanisms affecting extracellular arginine concentration, such as Arg1-mediated arginine depletion in the tumor microenvironment." (PMID 34037806, 2021). "MDSCs also upregulate iNOS and Arg-1 and, in this way, suppress T cell-mediated anti-tumor immunity." (PMID 34571894, 2021). "In syngeneic tumor-bearing mice, M2 TAMs express arginase-1, leading to depletion of L-arginine that is required for T cell activation." (PMID 34359674, 2021). "For instance, tumor-derived lactate potently induces ARG1 in TAMs via ERK1, 2/STAT3, and HIF-1α stabilization." (PMID 34476174, 2021). "Our findings provide the evidence that inhibition of ARG1/2 activity in tumor cells and myeloid cells in the TME unblocks antitumor responses in myeloid cells and NK cells, and improves the efficacy of the PD-1 inhibition." (PMID 34504786, 2021). "Differentiation is usually mediated by tumor-derived lactate via Akt/mTOR signaling pathway affecting the expression of pro-inflammatory cytokines and chemokines, Arg1, IL4Ra, and epithelial-to-mesenchymal transition (EMT)." (PMID 33670011, 2021). "When we determined the percentage of CD206- and Arg1-positive M2 macrophages in tumor tissue, we found that administration of macrophages treated with T47D-miR-138-5p exosomes increased the percentage of M2 cells." (PMID 34093857, 2021). "Upregulation of ARG1 in MDSCs not only trigger T cells inhibition but also promotes extracellular matrix remodeling, favoring tumor growth." (PMID 34336860, 2021). "We found that although AAA-CD4+ T-cell therapy increased the expression of genes encoding ARG1, iNOS, and COX2 in the tumor, it retained the ability to destroy established tumors in mice." (PMID 34625113, 2021). "The best model selected by the Akaike information criterion (AIC) contained three predictors, HPV status, tumor stage, and ARG1 mRNA level." (PMID 33807310, 2021). "Lactate induces ARG1 expression in TAMs and consequently affects the tumor cell proliferation and collagen synthesis through the production of ornithine and polyamines." (PMID 34390203, 2021). "Glycolysis or OXPHOS, FAS or FAO, IDO suppression or overexpression, Arg1 suppression or overexpression, etc. all can have a wide range of effects on tumor immunogenicity." (PMID 33670011, 2021). "ARG1-containing exosomes suppress proliferation of CD4+ and CD8+ T-cells in vitro and in vivo in OvCa mouse models by distributing ARG1 from tumor cells to antigen-presenting cells in secondary lymphoid organs." (PMID 34248988, 2021). "Upon accumulation in the tumor site, these tumor-suppressive TAMs drive immune suppression and angiogenesis through anti-inflammatory factors such as arginase (Arg1), TGF-β, IL-10, and VEGF." (PMID 34359588, 2021). "According to the results, OS of patients was negatively influenced by higher ARG1 mRNA level (HR = 1.4872, p = 0.0034) and increasing tumor stage (HR = 1.9602, p = 0.0246)." (PMID 33807310, 2021). "In our experiments, tumor cells inoculated with EVs-Hsp70 demonstrated significantly lower numbers of arginase-1-positive TAMs, that correlates with low concentrations of serum IL-10." (PMID 34716378, 2021). "The presented data provide a strong rationale for using an ARG1 inhibitor OAT-1746 to block the pro-tumor activity of GAMs." (PMID 34504786, 2021). "Of note, 3LL CM was ineffective in cells stimulated for differentiation with M-CSF, but both tumor CM alone were capable of slightly increasing Arg1 mRNA expression." (PMID 34680504, 2021).
tumor (continued). "N2 neutrophils show decreased ability to kill tumor cells and produce TGF-β and Arg-1 to inhibit anti-tumor immune response and promote tumor growth." (PMID 33814009, 2021). "Anatomical site affected the expression of ARG1, in both normal and tumor tissue, which was higher by six-fold in CA than in GA." (PMID 34439753, 2021). "In tumor-bearing mice, GrMDSCs exhibit lower levels of phagocytosis but higher levels of activation or production of arginase-1, myeloperoxidase (MPO) and ROS that suppress T cell function." (PMID 34359674, 2021). "As an addition to the Cox model, Kaplan–Meier estimator plots for HPV status, tumor stage, and ARG1 mRNA level were created." (PMID 33807310, 2021). "Unlike M1 macrophages that metabolize L-arginine by NOS2 to produce NO and kill tumor cells, M2-TAMs convert arginine to polyamines by activating expression of ARG1." (PMID 34885023, 2021). "Pro-tumor N2 TANs can inhibit T cell proliferation via expression of arginase 1 and induce T cell apoptosis via NO production." (PMID 35008550, 2021). "Treatment with CDA was associated with the reduction in expression of HCL tumour markers (CD20, CD11c) and increased expression of myeloid markers (CD14, CD68, CD66b, ARG1)." (PMID 34561502, 2021). "In turn, VEGF and Arginase-1 secreted by M2-polarized macrophages signal back to tumor cells and promote tumor growth." (PMID 34926283, 2021). "The counting data was confirmed by western blotting of tumor samples from all three experimental groups, which demonstrated that the level of arginase-1 in the ‘EVs-Hsp70’ tumors was approx. eightfold lower than that in the ‘Untreated’ group." (PMID 34716378, 2021). "Multiplex IHC images showed that mice receiving TPX therapy displayed reduced tumor-infiltrating Arg1+ M2 macrophages and Foxp3+ Treg cells, whereas the frequency of CD8+ cytotoxic T lymphocytes was not changed." (PMID 33809137, 2021). "Genetic ablation of Arg1 in the myeloid compartment of tumour-bearing mice was shown to reduce tumour growth, indicative of an immunosuppressive role for ARG1 in vivo." (PMID 33654093, 2021). "MDSCs can remarkably express arginase-1 and contribute to the development of the immunosuppressive tumor microenvironment." (PMID 34638729, 2021). "Univariate analyses revealed that Arg-1 and GPC-3 levels, tumor size, tumor number, lymph node metastasis, vascular invasion, and tumor stage were associated with tumor growth." (PMID 34715880, 2021). "Since ARG1 converts L-arginine to urea, we tested the levels of urea production in Gr1+CD11b+ MDSCs sorted from the spleen of tumor-bearing WT/KO mice." (PMID 34070449, 2021). "ARG1 plays a critical role in tumor promotion, as the ARG1-dependent pathway is responsible for generating cell proliferating substrates." (PMID 33514004, 2021). "First, MDSC levels in the tumor organoids were selectively reduced in the response group, with increased apoptosis and decreased ARG-1 expression in MDSCs after anti-PD-1 treatment." (PMID 33414378, 2021). "The suppression of essential anti-tumor T cell functions is, among others, mediated by the production of ROS, peroxynitrite, ARG1, proteases, indoleamine-2,3-dioxygenase (IDO) and NETs as well as the surface expression of PD-L1 and FasL on MDSCs." (PMID 34572138, 2021). "Macrophage colony-stimulating factor derived from Lewis lung carcinoma induced FASN expression in TAMs, stimulating tumor growth and angiogenesis in ARG1- and IL-10-dependent manner." (PMID 34742349, 2021). "The CM from NLRP7 overexpressing CRC cells, but not the control medium, upregulated the mRNA expression of VEGF and ARG1 which were used as indicators for the functional polarization of TAMs promoted by tumor signals." (PMID 33838681, 2021). "Although 22 additional tumor categories showed arginase immunostaining in a much smaller fraction of cases, strong and even moderate arginase-1 staining was exceedingly rare in these entities." (PMID 34943588, 2021).
tumor (continued). "Most arginase-1 positive cells appeared at the edges of the tumor tissues to trigger tumor growth and in the regions between the adipose and tumor tissues." (PMID 34638514, 2021). "ARG1 dependent pro-tumor TAMs stimulate angiogenesis through VEGF and IL6, promote invasion and proliferation via TGFβ and STAT3, and support immunosuppression through IL-10 and TGFβ." (PMID 34222022, 2021). "Our study demonstrates the involvement of neutrophil arginase-1 in cancer cell killing and highlights the importance and complex role of neutrophils in tumor surveillance and biology." (PMID 34131176, 2021). "Increased glycolysis results in increased lactic acid production, which ultimately induces TAMs to express tumor suppressor factors such as ARG1 and VEGFA." (PMID 33766119, 2021). "In turn, these GBex-reprogrammed GAMs, produce Arginase-1+ exosomes, which further disseminate immunosuppressive and tumor-growth promoting proteins, promoting tumor cell migration and proliferation." (PMID 34071306, 2021). "ARG1 is induced in tumour-infiltrating myeloid cells such as TAMs, MDSCs, and DCs through the secretion of tumour-derived factors and metabolites, including IL-4, IL-13, IL-6, M-CSF, GM-CSF, TGF-β, and cAMP." (PMID 34685679, 2021). "Genetic depletion of CD36 or inhibition of STAT3/5 restricted oxidative metabolism and immunosuppressive function in MDSCs, resulting in CD8+ T cell-dependent tumor delay due to reduced ARG1 and iNOS." (PMID 34742349, 2021). "In contrast, M2 TAMs suppress the immune response via the secretion of TGF‐β, IL‐10, and arginase 1 and stimulate tumor growth through the secretion of IL‐17, IL‐23, and pro‐angiogenic factors." (PMID 33252831, 2021). "We observed higher expression of Arg1, Il1a, and Rgs1 in macrophages from scaffolds compared with those from the primary tumor." (PMID 33782087, 2021). "We found the upregulation of ARG1/2 expression in GBMs, both in tumor cells and in tumor infiltrating microglia and monocytes/macrophages." (PMID 34504786, 2021). "The myeloid-derived suppressor cells (MDSCs) expressed high levels of arginase-1 and were recruited to the tumor tissues." (PMID 34638514, 2021). "The most significant issue to consider from a diagnostic point of view is the possibility of a contamination artifact in non-arginase-1 expressing tumor cells, adjacent to strongly arginase-1 positive normal liver cells." (PMID 34943588, 2021). "Conversely TAMs which metabolize arginine primarily through ARG1 are thought to have more pro-tumor activity." (PMID 34222022, 2021). "Arg1 expression levels were significantly higher than Arg2 mRNA levels both in microglia and Mo/MΦ immunosorted from tumor-bearing brain." (PMID 34504786, 2021). "The presence of MDSCs in tumor microenvironment induced by C. parvum can also be predicted by the detection of upregulated expression of ARG1, another immune suppressive factor which depletes arginine in the microenvironment." (PMID 34946170, 2021). "Next, we observed significantly higher infiltration by cells expressing only ARG1 both in the tumor parenchyma and stroma of HPV− patients (p = 0.0092 and p = 0.0002, respectively)." (PMID 33807310, 2021). "Arginase-1 is an inhibitory factor that depletes L-arginine from the tumor microenvironment and induces T cell anergy." (PMID 34638729, 2021). "Several preclinical studies have suggested the effectiveness of the ARG1-targeting approach in controlling tumour growth." (PMID 34685679, 2021). "TAMs isolated from C57BL/6 mouse tumour models treated with TSA exhibited decreased expression of the M2 markers Arg-1 and CD206, with heightened expression of the M1 markers iNOS and IL-6." (PMID 34944870, 2021). "It has been proposed that expression of CCL3, 4, and 5 in the tumor mass drives the recruitment of ARG1+CCR5+ LDNs18 in tumors." (PMID 34301813, 2021).
tumor (continued). "In this study we show that human neutrophil arginase, corresponding to arginase-1, is able to induce apoptosis in a number of tumor cells derived from different tissues." (PMID 34131176, 2021). "N2 TANs usually secreted more TGF-β and Arg-1, which lead to an immunosuppressive environment and contribute tumor cell immune escape." (PMID 33814009, 2021). "Icaritin reduced the expression of Arg-1 in tumor-infiltrating PMN-MDSCs from the tumors of orthotopic Hepa mice, and inhibited STAT3 activation in PMN-MDSCs." (PMID 33717093, 2021). "Neutrophils repress the response of tumor-suppressing CD8 + T lymphocytes by releasing nitric oxide synthase (iNOS) or arginase 1 (ARG1) upon TGFβ stimulation." (PMID 34048186, 2021). "In contrast, M2 macrophages exhibit an anti-inflammatory phenotype and secrete many pro-tumor factors, such as arginase 1 (ARG1)." (PMID 34742349, 2021). "Arginine availability is often very low in solid tumours due to increased consumption by rapidly dividing tumour cells and the overexpression of arginase-1 on tumour-infiltrating cells such as MDSCs." (PMID 34885108, 2021). "Consistent with the tumor suppression results, tumor-infiltrating M2 macrophages (Arg1+) were decreased in Beclin1-defective cell-derived tumors, compared with in scramble cell-derived tumors." (PMID 33809137, 2021). "High Arg-1 expression levels were associated with male (P = 0.043), HBV infection (P = 0.022), albumin levels over 35g/L (P = 0.018), and tumor size ≥ 5 cm (P = 0.047)." (PMID 34715880, 2021). "As previously shown, anti-inflammation-related genes (Arg1, Fizz1, and Ym1) were upregulated in the tumor-bearing brain hemisphere." (PMID 34440835, 2021). "Odc1 promotes tumor growth by increasing availability of polyamines from ornithine and acts downstream from Arg1." (PMID 34944584, 2021). "ARG1, a crucial immunosuppressive mediator, has been shown to boost immune evasion mediated by myeloid cells and promote tumor growth." (PMID 34282207, 2021). "Mechanistically, treatment response was associated with reduced expression of genes linked to suppressive myeloid phenotypes (CD11b, ARG1, CD206) in the tumor microenvironment." (PMID 34084172, 2021). "The role of Arginase-1 in tumor immune suppression and its potential as a drug target for cancer immunotherapy has culminated in the clinical development of CB-1158." (PMID 32647818, 2020). "Lactic acid produced by tumor cells, known to exert a critical role in inducing M2-like polarization of TAMs, is a key player in promoting ARG-1 expression by macrophages." (PMID 33212945, 2020). "M2 macrophages can secrete tumor-promoting factors, including Arg-1, TGF-b, and CCL18, which are proficient in tumor initiation and progression." (PMID 33052231, 2020). "Another example is nitroaspirine, which, in a mouse model, increased the number of tumor antigen-specific T cells and reduced both ARG1 and iNOS activity in MDSCs." (PMID 32849517, 2020). "Once trapped in those areas, macrophages shift from an inflammatory anti-tumor to a pro-tumor phenotype, exerting several functions, such as T cell inhibition by depletion of L-arginine via arginase-1, and promotion of angiogenesis by secreting VEGF-A." (PMID 33266104, 2020). "CB-1158 is an Arg1 inhibitor that reversed myeloid-mediated T cell inhibition in-vitro and suppressed tumour growth in-vivo." (PMID 33092283, 2020). "Vaccination with JAK2-mutant- and CALR-mutant-derived peptides will probably induce tumor-specific immune responses that will be further enhanced by co-vaccination with anti-regulatory epitopes, such as PD-L1- and ARG1-derived epitopes." (PMID 32630667, 2020). "In order to observe the phenotypic characteristics and the ARG1 expression level of tumor-infiltrating MDSCs from GAC patients, we collected cancerous and paracancerous tissues from 6 GAC patients to prepare mononuclear cell suspensions." (PMID 32415175, 2020).
tumor (continued). "Arginase-1 is abundantly expressed by tumor-infiltrating myeloid cells that promote tumor immunosuppression, which is relieved by inhibition of Arginase-1." (PMID 32647818, 2020). "Here, we evaluated the expression of ARG1 and found it to be elevated in both tumors and tumor-adjacent tissue as compared to normal mucosa." (PMID 32932854, 2020). "In turn, the tumor growth is influenced by TAM-releasing arginase 1 (Arg-1) induced by the lactic acid." (PMID 32499786, 2020). "MDSCs expressing the cationic amino acid transporter 2B (CAT-2B) import L-Arg in their cytoplasm where is it used as a substrate by ARG1, resulting in depletion of arginine in the tumor microenvironment and T cell neutralization." (PMID 32326073, 2020). "Amino acid degradation reactions mediated by IDO and ARG1 have become key factors in regulating tumor-induced immune tolerance." (PMID 33117713, 2020). "A high expression of arginase-1 results in the depletion of L-arginine in the tumor microenvironment, thereby inhibiting the proliferation of NK-cells and the proliferation and IFNγ production of cytotoxic T-cells." (PMID 32604862, 2020). "Recent studies confirm that ARG1 is expressed in activated M2 macrophages and participates in anti-inflammation, tumor immunity, tumor proliferation, metastasis and immunosuppression-related diseases." (PMID 32679719, 2020). "Previous studies using breast tumor cells (ZR-75-1) reported that ARG1-mediated polyamine production in TAMs increased tumor cell proliferation." (PMID 32726950, 2020). "In ovarian cancer, ARG1, using extracellular vesicles as a carrier, inhibits T-cell proliferation, which is beneficial to tumor growth and immune escape." (PMID 33511116, 2020). "Neutrophils are also able to suppress the immune response against tumor cells including the secretion of nitric oxide synthase (iNOS), or arginase 1 (ARG1) which suppress CD8+ T lymphocyte antitumor response." (PMID 32582698, 2020). "in their GI track show a lower expression of IL-4 that suppressed the activity of MDSCs on anti-tumor T-cells by downregulating arginase 1 expression." (PMID 33330446, 2020). "As a result, arginase-1 leading to depletion of L-arginine in the TME suppresses the ability of the T cells to exert their anti-tumor functions." (PMID 33384962, 2020). "The PCNs increased the number of cytotoxic CD8+ T lymphocytes and CD68+iNOS+ M1-like macrophages, induced minimal changes in CD4+ T lymphocytes, and decreased CD68+/Arg-1+ M2-like macrophages in tumor tissues." (PMID 32928251, 2020). "MCT4-mediated uptake of tumor-derived lactic acid increases vascular endothelial growth factor (Vegf) and Arg1 expressions in murine TAMs, which substantially supports tumor growth." (PMID 33171762, 2020). "Arginase-1(+) sEVs derived from TAMs promoted tumor cell migration and proliferation in glioblastoma and were considered as a distributor of proteins with pro-tumor functions in the TME." (PMID 33276428, 2020). "An in vivo study identified higher numbers of the immunosuppressive Arg1+ macrophages in tumors and showed that anti-programmed cell death-1 (anti-PD-1) treatment diminishes Arg1+ and increases Arg1- TAMs in the tumor microenvironment." (PMID 32326073, 2020). "ARG1 expression results in the consumption of amino acids, L-arginine, and L-cysteine ​in the tumor microenvironment." (PMID 33679700, 2020). "The ARG1 small molecule inhibitor CB-1158 blocks arginase, attenuates myeloid cell–mediated immune escape and tumor growth, and is beneficial to T-cell proliferation." (PMID 33511116, 2020). "MDSCs upregulated the expression of immune suppressive factors such as ROS, iNOS and Arg-1 to reduce T cells anti-tumor activity." (PMID 33613512, 2020). "By comparison, T‐MPs have shown a stronger induction of arginase 1 than tumor lysates or lactic acid." (PMID 32976623, 2020).